EIF4E3 (eukaryotic translation initiation factor 4E family member 3)
Description:
Recognizes and binds the 7-methylguanosine-containing mRNA cap during an early step in the initiation of protein synthesis. May act as an inhibitor of EIF4E1 activity (By similarity).
Synonyms: eIF-4E3; eIF4E-3; MGC39820
Tractability: No criterion of Open Targets' tractability assessment is met for any kind of drug.
Gene: Protein-coding gene on chromosome 3 (71,675,414 to 71,754,773, reverse strand). Ensembl gene ENSG00000163412.
Subcellular location (Human Protein Atlas): Nucleoli fibrillar center
Pathways (Reactome):
Disease: Dengue Virus Genome Translation and Replication
Immune System: ISG15 antiviral mechanism
Gene Ontology:
Molecular function: RNA 7-methylguanosine cap binding; translation initiation factor activity; RNA binding
Biological process: translational initiation
Cellular component: cytosol; eukaryotic translation initiation factor 4F complex
Genetic constraint (gnomAD): Loss-of-function variants: 25 observed, 27.79 expected, observed/expected ratio (o/e) 0.9, 90% interval 0.65 to 1.26. The upper end of that interval is the gene's LOEUF score, 1.26, which puts it in group 5 of 6, group 1 being the genes least tolerant of losing a copy. Missense variants: 242 observed, 213.85 expected, observed/expected ratio (o/e) 1.13, 90% interval 1.02 to 1.26. Synonymous variants: 97 observed, 78.5 expected, observed/expected ratio (o/e) 1.24, 90% interval 1.05 to 1.46.
Homologues: Orthologues: chimpanzee EIF4E3 (100% identical), macaque EIF4E3 (99% identical), pig EIF4E3 (95% identical), guinea pig EIF4E3 (88% identical), mouse Eif4e3 (88% identical), dog EIF4E3 (85% identical), rat Eif4e3 (84% identical), tropical clawed frog eif4e3 (73% identical), zebrafish eif4e3 (72% identical), Caenorhabditis elegans ife-4 (23% identical), Caenorhabditis elegans ife-5 (23% identical), Drosophila melanogaster eIF4E1 (23% identical), and 7 more. Paralogues in human: EIF4E2 (28% identical), EIF4E (26% identical), EIF4E1B (24% identical).
Diseases named in the same sentence as EIF4E3 in open-access papers:
EIF4E3 is named in the same sentence as 32 diseases in open-access papers, as found by Europe PMC text mining. Sharing a sentence is not in itself a finding about the gene and the disease. The quoted sentences say what the papers report.
breast carcinoma (4 papers, 2019 to 2025). "In parallel survival analysis of patients with breast cancer, overexpression of certain genes, including EIF4E3, improved survival rates." (PMID 39940786, 2025). "The results showed that 17 m7GRGs were risk factors and significantly impacted breast cancer prognosis, whereas NUDT10, NUDT3, EIF4E3, SNUPN, NUDT16, IFIT5 and EIF3D were favourable prognostic factors." (PMID 37353728, 2023). "The results showed that the expression levels of AGO2 and EIF4E3 were significantly lower in breast cancer cell lines than in the normal breast cell line, whereas the expression levels of DCPS and EIF4E were significantly higher." (PMID 37353728, 2023). "In our study, the expression level of EIF4E3 was significantly decreased in the BRCA group, indicating that EIF4E3 may function as a tumor suppressor gene in breast cancer, and its low expression may be associated with the progression of the disease." (PMID 40496561, 2025). "The results showed that the DMFS rates of AGO2 and EIF4E3 were significantly different, which may be related to the metastasis of breast cancer." (PMID 37353728, 2023). "The survival analysis suggested that DCAF13, EZR, MRPL13, APOBEC3C, and EIF4E3 might have a prognostic value for breast cancer." (PMID 30881302, 2019). "In addition, the DMFS rates of AGO2 and EIF4E3 were significantly different, which might be related to the metastasis of breast cancer." (PMID 37353728, 2023). "To more deeply evaluate the clinical impact of AGO2, EIF4E3 and EIF4E in breast cancer, we used the Kaplan–Meier plotter database to plot the DMFS (distant metastasis-free survival)-related Kaplan–Meier curves of AGO2, EIF4E3 and EIF4E." (PMID 37353728, 2023). "Breast cancer cell lines (MDA-MB-231, MDA-MB-468 and SKBR3) and a normal breast cell line (MCF-10A) were used to validate the expression levels of the signature m7GRGs (AGO2, EIF4E3, DCPS and EIF4E)." (PMID 37353728, 2023).
glioma (4 papers, 2019 to 2023). A benign or malignant brain and spinal cord tumor that arises from glial cells (astrocytes, oligodendrocytes, ependymal cells). "Analysis of data available on REMBRANDT and TCGA databases revealed that EIF4E1 and EIF4E3 mRNA levels are downregulated whereas EIF4E2 is overexpressed in gliomas." (PMID 31795417, 2019). "Thus, decreased expression of eIF4E1 and eIF4E3 together with increased eIF4E2 expression suggests a global repression of cap-dependent translation in gliomas." (PMID 31795417, 2019). "In contrast, immunohistochemical analysis of 10 refractory epilepsy tissues and 10 lower-grade gliomas (WHO grade II-III) tissues showed that lower-grade gliomas did not significantly increase in EIF4E2 and NCBP1 protein expression, while EIF4E, EIF4E3, and NCBP2 were increased." (PMID 36998056, 2023). "Immunohistochemistry analysis showed that EIF4E, EIF4E3, and NCBP2 were increased in lower-grade glioma tissues, while lower-grade glioma did not cause a significant difference in EIF4E2 and NCBP1 proteins." (PMID 36998056, 2023). "On the other hand, there were no considerable differences in the protein levels of EIF4E, EIF4E3, and NCBP2 between healthy brain tissues and lower-grade glioma tissues." (PMID 36998056, 2023).
diffuse large B-cell lymphoma (3 papers, 2016 to 2019). "MNKs, the eIF4E1 kinases regulated by the MAPK pathway, have a master role in the use of eIF4E1 or eIF4E3 to regulate mRNA recruitment in diffuse large B-cell lymphoma." (PMID 30717141, 2019). "Gartenhaus and colleagues found that treatment of diffuse large B-cell lymphoma cells with an MNK inhibitor, CGP57380, reduced eIF4E1-driven translation and resulted in a compensatory increase in eIF4E3-driven translation." (PMID 27626179, 2016).
medulloblastoma (3 papers, 2018 to 2021). A malignant, invasive embryonal neoplasm arising from the cerebellum. "Interestingly, Abdelfattah and coworkers published that eIF4E3 is required for G2/M progression in medulloblastoma cells." (PMID 33893802, 2021). "In addition, the overexpression of miR-584-5p was identified to suppress the self-renewal of medulloblastoma cells owing to its ability to target EIF4E3 and HDAC1." (PMID 33066509, 2020). "Certainly, the silencing of EIF4E3 and HDAC1 also represses the self-renewal capacity of medulloblastoma." (PMID 33066509, 2020). "In medulloblastoma patients, reduced expression of miR-584-5p correlated with increased levels of HDAC1/eIF4E3." (PMID 30382096, 2018). "Meta-analyses of Gene expression omnibus data sets GSE2824541 (n = 64) and GSE8521742 (n = 763) data sets revealed that SH3CT2 expression was markedly lower, while expression of eIF4E3 and HDAC1 was higher in all sub-types of medulloblastoma." (PMID 30382096, 2018). "Here, the authors show that miR-584 acts as a therapeutic adjuvant as it sensitizes medulloblastoma to radiation and chemotherapy by targeting HDAC1 or eIF4E3 to enhance spindle defects and DNA damage." (PMID 30382096, 2018). "MiR-584-5p overexpression or HDAC1/eIF4E3 silencing inhibited medulloblastoma stem cell self-renewal without affecting neural stem cell growth." (PMID 30382096, 2018).
osteosarcoma (3 papers, 2018 to 2021). A usually aggressive malignant bone-forming mesenchymal neoplasm, predominantly affecting adolescents and young adults. "A risk score model constructed based on four epigenetic modification-related genes (MYC, TERT, EIF4E3, and RBM34) can effectively predict the prognosis of patients with osteosarcoma." (PMID 34853590, 2021). "Our results showed that compared with osteoblasts, CPEB3, EIF4E3, RBM34, RPS27L, RPS29 and TDRD6 were down-regulated in U2OS and 143B, while NXT2, TERT, TLR8 and ZC3HAV1 were up-regulated in osteosarcoma cells." (PMID 34926575, 2021).
colon carcinoma (2 papers, 2020 to 2025). "miR-206 enhances wasting by decreasing the action of eIF4E3, and miR-21 inhibits the expression of transcription factor YY1 and eIF4E3, thus promoting muscle wasting in four different models: starvation, denervation, diabetes, and cancer cachexia induced by colon carcinoma." (PMID 33043011, 2020). "In colon cancer, most likely because of the lack of data, cross-correlation identified only three correlating groups (EIF4E3/MEX3A, SSR1/RPL39L, and PPARGC1B/CDKN2A)." (PMID 39940786, 2025).
epilepsy (2 papers, 2023 to 2025). A brain disorder characterized by episodes of abnormally increased neuronal discharge resulting in transient episodes of sensory or motor neurological dysfunction, or psychic dysfunction. "In this work, we screened five key m7G regulators in epilepsy and created a nomogram based on them to predict the risk of epilepsy, including METTL1, NUDT3, EIF4E3, LSM1, and SNUPN." (PMID 40658715, 2025). "Gene expression analysis of datasets GSE143272 and GSE190452 identified 8 differentially expressed m7G regulators (NUDT3, EIF4E3, LARP1, IFIT5, SNUPN, METTL1, EIF4A1, and LSM1) in epilepsy." (PMID 40658715, 2025). "The boxplot revealed that epilepsy patients had up-regulated expression levels of NUDT3, EIF4E3, LARP1, IFIT5, and SNUPN, and down-regulated expression levels of METTL1, EIF4A1, and LSM1." (PMID 40658715, 2025). "The cytological connection between eIF4E3, EIF4A1, and the beginning of epilepsy still need more research." (PMID 40658715, 2025).
prostate carcinoma (2 papers, 2017 to 2021). A carcinoma that arises from epithelial cells of the prostate gland. "This background was selected because eIF4E3 has been implicated in androgen-independent prostate cancer progression." (PMID 33893802, 2021). "eIF4E3 was used as a prey and screened against a peptide library originating from human prostate cancer cell lines." (PMID 33893802, 2021).
squamous cell carcinoma (2 papers, 2022 to 2023). A carcinoma arising from squamous epithelial cells. "Compared with normal tissues, the expression of EIF4E3 is lower in squamous cell carcinoma of the head and neck." (PMID 37664112, 2023). "Previous studies reveal a decrease in EIF4E3 expression increases tumor cell activity and aggressiveness in the head, and neck squamous cell carcinomas, acute myeloid leukemia, and breast cancer." (PMID 36473947, 2022).
hepatoma (1 paper, 2022). "EIF4E3 can promote translation, mRNA export, proliferation, and oncogenic transformation, and its related lncRNA LINC01352 was found to affect the growth and metastasis of hepatoma cells." (PMID 35754819, 2022).
liver cancer (1 paper, 2023). An epithelial or non-epithelial malignant neoplasm that arises from the liver. "Among the genes associated with the prognosis of liver cancer, the genes associated with shorter survival period are AGO2, DCPS, IFIT5, LARP1, NCBP2, NUDT10, and NUDT16; the genes associated with longevity are EIF4E3, EIF4G3, METTL1, NCBP1, NSUN2, NUDT11, NUDT4, and WDR4." (PMID 36845384, 2023).
lung carcinoma (1 paper, 2025). "In summary, poor survival is associated with PPARGC1B, EIF4E3, and SMAD9 low gene expression in breast, colon and lung cancer." (PMID 39940786, 2025). "Moreover, the downregulations of PPARGC1B, EIF4E3, and SMAD9 are associated with poor survival in breast, colon, and lung cancer patients." (PMID 39940786, 2025). "This study highlights the significant contribution of PPARGC1B, EIF4E3, and SMAD9 out of 11 RBP genes as prognostic predictors in patients with breast, colon, and lung cancers and their potential application in personalized therapy." (PMID 39940786, 2025). "The cross-correlation of EIF4E3/MEX3A has been defined in breast and lung cancers." (PMID 39940786, 2025). "Interestingly, most of the downregulated genes, including PPARGC1B, EIF4E3, and SMAD9, were classified with poor survival in breast, colon and lung cancer." (PMID 39940786, 2025).
male infertility (1 paper, 2022). The inability of the male to effect fertilization of an ovum after a specified period of unprotected intercourse. "Among the other validated hits were proteins involved in the ubiquitin proteasome system (STAMBP and MYLIP), transcription (MTA1, PKNOX2), translation (EIF4E3), male infertility (RABL2A, DAZAP1), and virus-induced oncogenesis (MTA1)." (PMID 35452674, 2022).
melanoma (1 paper, 2022). A malignant, usually aggressive tumor composed of atypical, neoplastic melanocytes. "The current research describes for the first time that the risk scores created by EIF4E3, LARP1, NCBP3, and IFIT5 can serve as independent prognostic factors for melanoma." (PMID 36473947, 2022). "To understand the role of m7GMRRGs in melanoma prognosis in further detail, we selected four m7GMRRGs (EIF4E3, LARP1, NCBP3, and IFIT5) to develop prognosis prediction model." (PMID 36473947, 2022).
myocardial infarction (1 paper, 2023). Gross necrosis of the myocardium, as a result of interruption of the blood supply to the area, as in coronary thrombosis. "However, EIF4E3 also promotes angiogenesis in the region surrounding myocardial infarction." (PMID 36952494, 2023).
neuroblastoma (1 paper, 2021). Neuroblastoma (NB) is the most common solid, extracranial childhood tumor. "While eIF4E1 was found in all cell lines tested, the expression level of eIF4E3 varied considerably (it was undetectable in the non-tumoural cell lines NIH3T3, MEF and MRC5, but highest in the mouse neuroblastoma cell line N2a)." (PMID 33893802, 2021).
plasmacytoma (1 paper, 2016). Plasmacytoma is a localized mass of neoplastic monoclonal plasma cells that represents approximately 5% of all plasma cell neoplasms. "EEF1A2 is a translation elongation factor gene that was previously shown to promote survival of mouse plasmacytoma cells, whereas EIF4E3, RND3/RhoE and FAM129A/Niban encode proteins that participate in various facets of cap-dependent translation initiation (described in more detail below)." (PMID 27626179, 2016).
Stroke (1 paper, 2023). Sudden impairment of blood flow to a part of the brain due to occlusion or rupture of an artery to the brain. "The hsa_circ_0018657/hsa-miR-198/EIF4E3 pathway was explored as the regulating axis in AF-related stroke." (PMID 36952494, 2023). "Co-expressed hub genes of EIF4E3, ZNF595, ZNF700, MATR3, ACKR4, ANXA3, SEPSECS-AS1, and RNF166 were significantly associated with AF-related stroke." (PMID 36952494, 2023). "Based on the results of DEG3 and ROC curves in GSE66724 and GSE58294, we filtered eight hub genes of AF-related stroke (AUC > 0.8), including EIF4E3, ZNF595, ZNF700, MATR3, ACKR4, ANXA3, SEPSECS-AS1, and RNF166." (PMID 36952494, 2023). "Finally, we constructed a circRNA-miRNA-mRNA network of AF-related stroke and screened out the hsa_circ_0018657/hsa-miR-198/EIF4E3 axis as an important regulatory pathway in the development of AF-related stroke." (PMID 36952494, 2023). "The hsa_circ_0018657/hsa-miR-198/EIF4E3 pathway could be an important regulating axis in AF-related stroke." (PMID 36952494, 2023). "Based on previous studies, we believe that miR-198 could play an important role in the development of AF-related stroke by binding to the 3’UTR of EIF4E3." (PMID 36952494, 2023). "The hsa_circ_0018657/hsa-miR-198/EIF4E3 axis could play an important role regulating the development of AF-related stroke." (PMID 36952494, 2023). "In the present study, EIF4E3 was explored as a potential molecular signature for AF patients with a high probability of stroke occurrence, which may play an important role in the development of AF-related stroke." (PMID 36952494, 2023). "EIF4E3 is the target of hsa-miR-198, and hsa-miR-198 is the target of hsa_circ_0018657, suggesting that hsa_circ_0018657/hsa-miR-198/EIF4E3 could be an important pathway regulating the development of AF-related stroke." (PMID 36952494, 2023). "Hub genes EIF4E3, ZNF595, ZNF700, MATR3, ACKR4, ANXA3, SEPSECS-AS1, and RNF166 have potential as novel biomarkers and therapeutic targets in AF-related stroke." (PMID 36952494, 2023). "The hub genes of EIF4E3, ZNF595, ZNF700, MATR3, ACKR4, ANXA3, SEPSECS-AS1, and RNF166 may link AF and secondary stroke." (PMID 36952494, 2023). "Results showed that the expression of EIF4E3, ANXA3, and hsa_circ_0018657 was significantly higher in AF-related stroke patients than those in AF patients without stroke, which was consistent with the bioinformatic analysis." (PMID 36952494, 2023).